RNU4-53P (RNA, U4 small nuclear 53, pseudogene)
Gene: Small nuclear RNA gene on chromosome 9 (36,267,783 to 36,267,922, forward strand). Ensembl gene ENSG00000222760.
Homologues: Orthologues: chimpanzee U4 (99% identical), macaque U4 (81% identical), rabbit U4 (54% identical), dog U4 (48% identical), rat LOC120094543 (48% identical). Paralogues in human: RNU4-90P (64% identical), RNU4-49P (62% identical), RNU4-25P (61% identical), RNU4-81P (60% identical), RNU4-51P (59% identical), RNU4-10P (59% identical), RNU4-91P (59% identical), RNU4-36P (58% identical), RNU4-75P (58% identical), RNU4-17P (57% identical), RNU4-50P (57% identical), RNU4-59P (57% identical), and 82 more.